GZMB (granzyme B)
Diseases named in the same sentence as GZMB in open-access papers (continued):
Sharing a sentence is not in itself a finding about the gene and the disease.
tumor (continued). "The bsAb induced potent T-cell-directed cytotoxicity, along with secretion of IFN-λ, TNF-α, and granzyme B, against various types of HER2-positive tumor cells in vitro, including A549, NCI-H460, SKOV-3, A1847, SKBR3, and MDA-MB-231." (PMID 39066446, 2024). "An increase in GzmB+CD8+ T cells was observed upon FKBP12F36V-KRASG12V degradation, suggesting an enhanced cytotoxic T cell–mediated clearance of tumor cells." (PMID 39718828, 2024). "Compared to conventional CAR-T cells, CAR-ss-T cells produced higher levels of interferon-γ (IFN-γ), IL-2, tumor necrosis factor-α (TNF-α) and granzyme B (GZM) against MSLN-expressing HGC27 and MKN45 tumor cells." (PMID 38368374, 2024). "Chimeric antigen receptor-T (CAR-T) cell-derived exosomes (CAR-T-Exo) contain tumor-targeted CAR and cytotoxic particles (granzyme B [GZMB] and perforin [PRF]), which can be used in the treatment of tumors and are considered potential carriers of paclitaxel." (PMID 38994350, 2024). "The immunofluorescence staining results demonstrated a significant production of Granzyme B in the DA‐L‐DSA/ anti‐PD‐1 combinatory‐treated group, indicating activation of cytotoxic T cells within the tumor." (PMID 39073756, 2024). "High-ANXA2 was correlated with decreased proportion of granzyme B+ CD8+ T cells (Spearman’s ρ = − 0.40, P = 0.01), and increased TIM-3+ (Spearman’s ρ = 0.43, P < 0.001) and CTLA4+ (Spearman’s ρ = 0.49, P < 0.001) tumor-infiltrating lymphocytes." (PMID 38519766, 2024). "NK-92 cells also express high levels of cytotoxic effector molecules, such as perforin, granzyme B, FasL, TRAIL, and TNF-α, consistently inducing high cytotoxic activity against tumour cells." (PMID 39450176, 2024). "Specifically, compared with DMSO treatment, UA treatment increased the expression of IFN‐γ, TNF‐α, IL‐2, CD107a, and granzyme B in OT‐I CD8+ CTLs and enhanced the cytotoxic activity against antigen‐pulsed EL4 tumor cells in vitro." (PMID 38447147, 2024). "In addition, evidence also indicates that B cells may have antitumor activity, which is mediated by killing of tumor cells through expression of TNFs/receptor proteins or production of granzyme B, IL12-mediated activation of NK cells, or antibody-dependent cell-mediated cytotoxicity." (PMID 39028943, 2024). "The up-regulation of granzyme B was observed after 48 h of co-culture, indicating that T cells had an IgG-T-TCE-NY-induced augmented ability to kill tumor cells." (PMID 38672132, 2024). "Overall, the GzmA-GSDMB and GzmB-GSDME pathways play a crucial role in the body's antitumor immune response, offering novel insights for tumor immunotherapy." (PMID 38987821, 2024). "Treatment with this monoclonal antibody decreased levels of GZMB/CCL5 expressed per CD4+ T cell harvested from T3 or F244 tumour-bearing mice." (PMID 39048822, 2024). "ITGAE is associated with a group of genes that have a cytotoxic function in CD8 cytotoxic T cells (CTSW, GNLY, NKG7, PRF1, GZMB, KLRK1) up-regulated in the tumor, identifying resident CD8 T cells in the tumor to have a highly cytotoxic and activated phenotype." (PMID 39548591, 2024). "Deletion of BATF in REGNASE-1-null cells hampered cell proliferation and survival and decreased IFN-γ, GZMB, and TNF-α expression, dampening anti-tumour capability." (PMID 38581063, 2024). "GZMB, a key effector molecule in immune cell anti-tumor activity, can be produced by B cells upon BCR recognition of tumor antigens, directly killing tumor cells." (PMID 39519376, 2024). "Treatment with tretinoin induces a robust anti-tumor CD8+ T cell response, increasing proliferation, expression of effector molecules IFNγ, granzyme B and perforin, as well as activation and cell migration markers." (PMID 38350880, 2024). "Of note, the percentage of either Granzyme B-positive or IFN-γ-positive CD8+T cells was also significantly potentiated, suggesting the enhanced anti-tumor capacity of CD8+T cells after the combined treatment." (PMID 38291473, 2024).
tumor (continued). "Intriguingly, GZMB also stimulates caspase-3 to segment GSDME, establishing a reinforcing antitumor cycle and contributing to tumor inhibition." (PMID 38304430, 2024). "Despite the overall increase in CD8+ T cells within PDAC tumours upon IGF blockade, the proportion of CD8+ T cells concomitantly expressing granzyme B, a marker of T cell functional activity, remains low after IGF blockade." (PMID 39165364, 2024). "During the execution of these anti‐tumor immune processes, the levels of certain typical pro‐inflammatory cytokines, namely, IL 2, TNF‐α, IFN‐γ, and granzyme B (GzmB), were analyzed to assess the activation of the immune system." (PMID 38742454, 2024). "Dual blocking of PD-1 and A2aR significantly enhanced the expression of IFN-γ and GzmB in tumor-infiltrating CD8+T cells, thereby enhancing the inhibition of CD73+ tumor growth and prolonging the survival of mice." (PMID 39188712, 2024). "Of note, flow cytometry analysis also revealed that the percentages of Granzyme B+ and IFN-γ+CD8+T cells were increased after the treatment with HA15, indicating the potentiation of the anti-tumor capacity of CD8+T cells in TME." (PMID 38291473, 2024). "The treatment increased the number of CD8+ T cells infiltrating the tumor and increased levels of IFN-γ, GZMB, and TNF-α while decreasing the number of Treg cells in the tumor, blood, and spleen." (PMID 37397393, 2023). "We proved that CAR-Exos expressed the granzyme B and perforins internally, which resulted in the death of MLSN-expressing tumor cells." (PMID 37308954, 2023). "Moreover, the immunofluorescence density of granzyme B+ (GZMB+) and interferon-γ+ (IFN-γ+) CD8+ T cells also significantly increased in Phf8-deficient CT26 tumors, implying that depletion of tumor PHF8 promotes adaptive anti-tumor CD8+T cell immune responses and results in tumor growth repression." (PMID 37454216, 2023). "Tumor suppression coincided with an increase of CD8+ T cells, granzyme B staining, and M1-like macrophages." (PMID 36765611, 2023). "ILC1s express several molecules driving cytotoxicity including granzyme A, granzyme B, granzyme C, and TRAIL, and are highly efficient in killing tumor cells demonstrating a potent immunosurveillance and killing mechanism of ILCs." (PMID 38567059, 2023). "Activated NK cells can synthesize and secrete a variety of killing mediators, such as perforin, granzyme B, and TNF-α, which can regulate immunity and directly kill tumor cells." (PMID 36937004, 2023). "PKM2 knockout (PKM2KO) T cells following co-culture with HKP1-ova-GFP tumor cells showed higher levels SlamF6 and TCF1 with concomitant decreases in GzmB, IFNγ, and TNFa." (PMID 37790365, 2023). "The expression level of gene sets related to cytotoxic T cell activation (perforin, granzyme A, and granzyme B), costimulation (CD80 and CD86), and immune checkpoints (LAG3, CTLA4, PD-L1, and PD-1) was found to be increased in the tumor tissue." (PMID 37606040, 2023). "IHC staining on tumor tissues from subcutaneous tumors indicated the elevations of CD3, CD8, and GZMB signals in subcutaneous tumors of AKR/shPES1 compared with that of AKR/SCR." (PMID 36959575, 2023). "Targeting this ADO-receptor results in reduced metastasis, improved tumor control and delayed tumor initiation in experimental models, by enhancing NK-mediated cytotoxic activity in a PRF1 and GZMB-dependent manner." (PMID 37753093, 2023). "Subsequent analysis of effector molecules in the tumour microenvironment revealed increased secretion of IFN‐γ and Granzyme B after cryoablation." (PMID 37157934, 2023). "Another work in the B16.F10 model also demonstrated that TLR7/9 stimulation with imiquimod can trigger CCL2 release by MCs to efficiently recruit plasmacytoid DCs at the tumor site, which, in turn, can directly kill tumor cells via TRAIL and granzyme B." (PMID 37376140, 2023).
tumor (continued). "Through the active recognition of CAR-Exos and the passive movement of inhalation, the treatment exhibited a better anti-tumor effect than free PTX, which was attributed to granzyme B and perforin from CAR-Exos and the therapeutic effects of PTX." (PMID 37308954, 2023). "Thus, the Ce6-PDT-associated decrease in PD-1/PD-L1 interaction is linked with increased tumor cells death in distant tumors with the enhanced frequency of CD8+ T cells through the release of IL-2, suppression of CD39+ T cell activity, and increased Granzyme B levels." (PMID 36944686, 2023). "Because the tumor-killing effects of CD8+ T cells are mediated by cytotoxic proteins and cytokines, we further analyzed the expression of granzyme B, perforin and IFN-γ40,41." (PMID 37031188, 2023). "Our research in NSCLC showed that anti-tumor function of CD36+CD8+ T cells was impaired, with less production of GZMB and INF-γ and higher expression of PD-1 and TIGIT." (PMID 37085798, 2023). "A reduced fraction of CTCL skin NK cells expressed the maturation marker CD57, the cytotoxic protein granzyme B and the activation marker CD69, indicating reduced tumor-killing abilities of the NK cells." (PMID 37691935, 2023). "Authors also found that the single treatment with CD40 ab therapy in mice decreased the PD-1 expression on tumor cells and also changed the T cell phenotype, which helped increase the expressions of IFN-gamma, Ki-67, and granzyme-B, helping clear the tumor." (PMID 36769180, 2023). "A substantial part of these KLRK1+ CD8+ T cells, especially in the tumor, were bona fide KILR cells as shown by their high expression of IL-7R and GZMB and low expression of CD49d." (PMID 36705564, 2023). "Both activated CD8+ T cells and NK cells show cytolytic activity against tumor cells by secreting several cytolytic molecules, such as granzyme A (GZMA), GZMB, and perforin (PRF1), showing good prognoses in various types of cancers." (PMID 38203530, 2023). "RA potentially elicited tumor cell ICD and induced effective T cells activation and boosted the production of IFN‐γ and GZMB by tumor‐infiltrating CD8+ T cells, indicating that RA mobilizes T cell immunity for tis anti‐tumor effect." (PMID 36876644, 2023). "We examined the expression of granzyme B, interferon (IFN)-γ, and tumor necrosis factor (TNF)-α all of which play a major role in cell contact-independent tumor cell killing." (PMID 37100864, 2023). "The expressions of CD44 and CD69 and those of granzyme B (GrB) and IFN-γ, which is involved in tumor eradication, were analyzed by flow cytometry." (PMID 37875555, 2023). "Consistently with the M1 activation pattern demonstrated for the VSSP-BMDMs, the frequency of tumor-infiltrating CD8+ T cells secreting IFNγ and Granzyme B were increased in the TME, suggesting an immunostimulatory potential of VSSP-BMDMs." (PMID 37055829, 2023). "The secondary endpoint is augmentation of tumor infiltration of the tumor microenvironment as determined by a quantitative immunofluorescence score (QIF) measuring CD3+ lymphocytes and granzyme B expression." (PMID 37835379, 2023). "As expected, PES1 knockdown dramatically enhanced the infiltration of CD8+ CTL in AKR subcutaneous tumors and also increased the percentages of GZMB+/CD8+ CTL, a marker of activated CD8+ CTL, in tumor microenvironment compared to SCR group." (PMID 36959575, 2023). "The percentage of both CD8+ T cells and CD8+ granzyme B+ T cells were increased with POLQ knockdown, suggesting increased T cell–effector function in the tumor microenvironment in that setting." (PMID 36976649, 2023). "eNK cells expressed granzyme B and perforin and displayed surface TRAIL and FasL, the latter detected only following incubation with tumor cells, in agreement with a previous report." (PMID 37919293, 2023). "Granzyme B is primarily a CD8+ T cell (and NK cell) cytotoxic molecule effective against tumor cells." (PMID 37760508, 2023).
tumor (continued). "In order to determine if VSSP administration showed an effect on tumor-infiltrating lymphocytes, we determined by FACS the production of INFγ and Granzyme B (GraB) in the CD8+ subset." (PMID 37055829, 2023). "Previous reports have shown that when GZMA cleaved GSDMB or GZMB cleaved GSDME, NK cells and CD8(+) T cells directly triggered pyroptosis of tumor cells." (PMID 37221570, 2023). "In addition, the combination of the knockdown of SIRT7 and anti-PD-1 antibody treatment could induce more infiltration of CD8+T cells and GzmB-positive CD8+T cells in the implanted tumor, indicating that the combination treatment approach triggered more prominent activation of anti-tumor immunity." (PMID 36918544, 2023). "Single-cell RNA-seq of PyMT tumor CD8+ T cells revealed unique signatures for early effectors (Il7r, Tcf7), exhausted (Pdcd1, Tox), and ILTCKs (GzmB, Klrb1c, Fcer1g)." (PMID 37892995, 2023). "When curcumin and PD-L1 antibody were combined, tumor development was considerably inhibited, and co-cultured CD8+ T cells released more IFN-γ and GZMB." (PMID 37397393, 2023). "CD8+ T cells inhibit tumor growth by secreting cytokines, such as interferon (IFN)-γ, granzyme B, and tumor necrosis factor-α (TNFα)." (PMID 37901252, 2023). "Consistently, immunohistochemistry staining confirmed that mRIP3R479K overexpression increased tumor Gr1+ MDSC, while inhibited CD8+ T cells and Granzyme B+ cytotoxic cells." (PMID 37005412, 2023). "Vaccination with GPC3144‐152 induced tumor‐specific CD8+ T cells that secreted high levels of IFN‐γ and granzyme B, and had potent cytotoxicity against TYST in a dose‐dependent manner." (PMID 37986544, 2023). "Ldha is associated with the HIF-1 signaling pathway, and it has been documented that knockdown of HIF-1α enhances the tumor-killing capacity of NK cells and upregulates expression levels of IFN-γ, granzyme B, and Cd107a in splenic NK cells." (PMID 37039643, 2023). "CD8+ T cells recognize specific antigenic peptides on the surface of tumor cells and release large amounts of IFN-γ, granzyme B, and perforin to destroy tumor cells." (PMID 37275874, 2023). "CD8+ tumor-infiltrating lymphocytes (TIL) are the key cells of the antitumor response through the release of enzymes such as perforin and granzyme B (Grb), which induce apoptosis in cancer cells." (PMID 37511133, 2023). "Primarily, paracrine TGF-β attenuates the cytotoxicity and the tumor-killing ability of CD8+ T cells through its action on αβ T cells, thereby reducing the percentage of GzmB+ CD8+ TILs." (PMID 37483603, 2023). "Flow cytometry further validated that tumor-infiltrating CD8+ T cells from the KO group presented strong production of IFN-γ and granzyme B." (PMID 36650153, 2023). "In our previous study, an increase in peripheral blood of CD8+ granzyme B+ T cells was observed in eCPMV-treated patients, which aligns with the role of Th17 cells in generating cytotoxic CD8+ T cells for tumor defense." (PMID 37762335, 2023). "The percentages of tumor-infiltrating CD4 and CD8 T cells as well as interferon (IFN)-γ and granzyme B (GZB) secretion were higher in the methionine-treated group than in the PBS-treated group." (PMID 37147330, 2023). "Consistent with the greater immunogenicity of MMRd tumors, MMRd T cells were enriched in programs involving cytotoxicity (granulysin, granzyme B, perforin) and exhaustion (PD-1, TOX, LAG3), suggesting chronic stimulation of tumor-reactive T cells." (PMID 37492581, 2023). "CD8 T cell cytotoxicity can be mediated by perforin and granzyme B, but IFN-γ is also capable of inducing tumor cell cytostasis and death particularly in combination with TNFα." (PMID 38000024, 2023). "DnTGFBRII was found to decrease the proportion of Tregs in tumor tissue, increase differentiation of T cells into effector cells, and induce effector molecule production such as IFN-y, granzyme B, and perforin." (PMID 37754534, 2023).
tumor (continued). "Treatment with GPC3144‐152 enhanced the infiltration of CD8+ T cells into the tumor environment and their cytotoxicity against TYST tumors in vivo by up‐regulating granzyme B and IFN‐β expression, but down‐regulating GPC3 expression in the tumors." (PMID 37986544, 2023). "The nasal nano-vaccine-induced T-cell-mediated antitumor mucosal immune response was shown to increase tumor-specific production of IFN-γ and granzyme B by lung-derived CD8+ T cells." (PMID 36839766, 2023). "Ldha/b-DKO mice exhibited decreased numbers of tumor-infiltrating CD4+ and CD8+ T cells and decreased frequencies of tumor-infiltrating IFN-γ–producing and granzyme B–producing CD4+ and CD8+ effector T cells." (PMID 36821379, 2023). "A further study of tissue from 13 treatment-naïve patients with resectable NSCLC used cytometry by time-of-flight and IMC to describe a population of CD8+PD-L1+ tumour-infiltrating T-cells with low levels of expression of PD-1, CD103, GZMB and IFN-γ." (PMID 37835491, 2023). "The results of immunofluorescence staining for tumor areas showed that the LNP-siRNA & aPD-L1 group had the widest distribution of CD8+ T cells, accompanied by the highest expression of granzyme B and the lowest expression of PD-L1." (PMID 38093288, 2023). "SC144@HABN treatment promoted strong tumor-infiltration of CD8+ T-cells and increased their proliferation and functionality in vivo, as shown by increased expression of Ki67+ and granzyme B+ on CD8+ T-cells." (PMID 37553327, 2023). "Up-to-date several Hsp70-targeting tools (e.g., tumor penetrating peptide (TPP), monoclonal antibody cmHsp70.1 and its Fab fragment, serine protease granzyme B, anticalins) have been successfully employed for tumor imaging and therapy in preclinical models." (PMID 37932378, 2023). "M6PR is a receptor for granzyme B (GrzB) released by activated cytotoxic T cells, and the binding of M6PR to GrzB leads to tumor cell death." (PMID 37689699, 2023). "Adoptive transfer of BVax-activated CD8+ T cells into tumor-bearing brains led to T cell reactivation with higher TCF-1 expression and elevated granzyme B production compared to DC-activated CD8+ T cells." (PMID 38268923, 2023). "HT-29 tumor cell killing by tumor CD4 T cells was accompanied by markedly increased intracellular expression of perforin and GZMB, as well as the surface expression of CD107a, a marker for degranulating CTLs." (PMID 37185301, 2023). "Meanwhile, the levels of CD8+ T cell effector molecules GZMB and IFN‐γ within tumor microenvironment (TME) also dramatically increased in RA‐treated group, implying that RA enhances the activation of effective T cells in vivo." (PMID 36876644, 2023). "While we detected higher levels of markers associated with effector responses, such as CD20, GZMB, and CD56 in ‘immune-rich cancer cell islet’ regions, additional expression of markers such as PD-1 and FOXP3 in the same regions may reflect mechanisms associated with tumor growth in NPC." (PMID 37046826, 2023). "To assess the activation status of the infiltrated CD8+ T cells in the tumor microenvironment, we performed coimmunofluorescence analyses of CD8 and Granzyme B, the latter a marker indicative of activated CD8+ T cells, on tumor sections." (PMID 36976649, 2023). "Despite T cells with stemness characteristics exhibiting lower secretion of IFN-γ, TNF-α, and granzyme B (GZMB), their capacity for tumor cell destruction is diminished." (PMID 38169800, 2023). "As a consequence, lipid-laden NK cells exhibit decreased production of granzyme B and IFN-γ, which ultimately results in a diminished anti-tumor effect." (PMID 37700339, 2023). "CD8+TILs can exert anti-tumor functions through several pathways such as the release of GZMA and GZMB, Fas-Fas ligand pathway-mediated apoptosis, and secretion of inflammatory cytokines like IFN-γ and TNF-α." (PMID 37781365, 2023).